HIF1A (hypoxia inducible factor 1 subunit alpha)
Diseases named in the same sentence as HIF1A in open-access papers (continued):
Sharing a sentence is not in itself a finding about the gene and the disease.
Cerebral ischemia (continued). "Our results showed that inhibiting HIF-1α/NLRP3 signaling resolved the MDA/SOD imbalance after thalamic hemorrhagic stroke, which was corroborated by previous studies showing that HIF-1α and NLRP3 inflammasome activation increases brain oxidative stress after cerebral ischemia in rats." (PMID 36944982, 2023). "Among HIF-1α, MKP-1 and K-RAS, the ischemia-related let-7a putative targets examined in the present study, only HIF-1α seems to take part to the protective mechanism exerted by anti-let7a in brain ischemia and involved in remote postconditioning neuroprotection." (PMID 33204336, 2020). "Although VEGF is induced in ECs through HIF-1α, and the expression of HIF-1 and HIF-2 are increased in the border area of ischemic stroke, the mechanisms by which VEGF gene expression is regulated during cerebral ischemia remain unclear." (PMID 26834557, 2016). "This activity is mediated, at least in part, by inhibition of inflammatory responses (i.e., HIF-1α, iNOS expression) and apoptosis (i.e., TNF-α, active caspase-3), resulting in a reduction of infarct volume and improvement in neurobehavior in rats with cerebral ischemia." (PMID 24285977, 2013).
Stroke (130 papers, 2009 to 2026). Sudden impairment of blood flow to a part of the brain due to occlusion or rupture of an artery to the brain. "The cellular model study revealed that the induction of HIF-1α after hypoxia-ischemia is impeded in cybrids harboring stroke-susceptible F1 mtDNA haplogroups." (PMID 32796743, 2020). "HIF-1α is a major transcription factor for several genes associated with angiogenesis, energy metabolism, cell survival, and neuroprotection after stroke, and HO-1 protects against ischemia/reperfusion (I/R) after brain injury." (PMID 30153269, 2018). "For example, microglia pyroptosis is thought to be caused by elevated HIF-1α in stroke." (PMID 35132350, 2022). "Therefore, the serum level of CTSB and HIF-1α in stroke patients remains inconclusive and their association with MBE after stroke needs further investigation." (PMID 34493232, 2021). "However, stroke-susceptible haplogroup F1 exhibited the least elevated HIF-1α level; whereas haplogroup B exhibited the most elevated level in response to hypoxia-ischemia." (PMID 32796743, 2020). "Therefore, utilizing miR-18a mimics or inhibitor to regulate HIF-1α expression may have alleviating or therapeutic effects on neurological damage caused by hypoxia such as stroke." (PMID 38879468, 2024). "Moreover, the results may provide a base for our future study regarding the regulation of HIF-1α on the BDNF/TrkB/CREB pathway in the biochemical processes underlying post-stroke synaptic plasticity." (PMID 32670026, 2020). "Additionally, the results may provide a base for our future study regarding the regulation of HIF-1α on the BDNF/TrkB/CREB pathway in the biochemical processes underlying post-stroke synaptic plasticity." (PMID 32670026, 2020). "Moreover, the expression of HIF-1α is associated with GBM patients previously with stroke." (PMID 29312585, 2017). "In view of that there could be a pathogenic synergy between the two disease processes, stroke and AD might effectively share common risk factors: in this scenery the role of Pin1 in HIF-1α isomerization and degradation may outcome as central mechanism in vascular damages vs. AD and vice versa." (PMID 24478626, 2014). "A growing body of evidence revealed the role of HIF‐1α in facilitating neurorepair and functional recovery following stroke and TBI by upregulating VEGF expression and promoting angiogenesis." (PMID 40277259, 2025). "We have recently reported that ketosis-stabilized HIF-1α regulates the inflammatory response and contributes to neuroprotection in a rat stroke model." (PMID 40272769, 2025). "Current evidence indicates that NBP promotes post‐stroke angiogenesis through multiple pathways, including Shh and HIF‐1α/VEGF signaling, however, the involvement of the Akt/GSK‐3β/β‐catenin pathway remains to be elucidated." (PMID 41373119, 2025). "HIF-1α accumulation has dual effects, including cell death and cell survival, in neurovascular diseases such as stroke, traumatic brain injury (TBI), and AD." (PMID 38674050, 2024). "Higher HIF-1α levels have been significantly correlated with the initial stroke scale score, indicating a worse outcome." (PMID 38674050, 2024). "This review presents the molecular mechanisms by which HIF-1α is involved in the pathogenesis of CNS injuries, such as stroke, traumatic brain injury, and Alzheimer’s disease." (PMID 38674050, 2024). "A meta-analysis of post-stroke liraglutide administration in rodents shows that liraglutide downregulates HIF-1a and NK-kB, which are key activators of the inflammasome." (PMID 41424495, 2024). "One possible explanation is that the temporal regulation of HIF1α in stroke is complex and it has many cell type-specific downstream targets in the brain." (PMID 39520909, 2024). "In the following sections, the relationship between HIF-1α and inflammasomes in neurovascular diseases, such as stroke, TBI, and AD, is discussed." (PMID 38674050, 2024).
Stroke (continued). "Some contradictory results, however, have been proposed while trying to interpret the specific mechanism of HIF‐1α on stroke." (PMID 39295108, 2024). "In a stroke model, astrocytes promote angiogenesis and facilitate neurological recovery by activating the HIF-1α/VEGF signaling pathway." (PMID 39102510, 2024). "The molecular and migratory capacities of SVZ neuroblasts are altered in stroke; genes such as Hif-1α or Notch4 are upregulated, and molecules such as MMPs are overexpressed in SVZ neuroblasts in response to stroke in order to facilitate emigration." (PMID 37047560, 2023). "Cardiovascular function pathways regulated at 5-h post-stroke that correlated with 90d outcomes included Adrenomedullin signaling pathway, Renin–Angiotensin Signaling and HIF1α Signaling." (PMID 36691064, 2023). "The signaling pathway of HIF-1α plays a role in stroke-related processes such as inflammatory response, angiogenesis, and neuroprotection." (PMID 37351420, 2023). "Recently, attention has been focused on the role of HIF-1α in NSCs during nerve regeneration after traumatic brain injury and stroke; furthermore, VHL, upstream of HIF-1α, is thought to play an important role in this process." (PMID 36835292, 2023). "Zinc improves neurological recovery by promoting angiogenesis via the astrocyte-mediated HIF-1α/VEGF signaling pathway in experimental stroke." (PMID 37760793, 2023). "Hypoxia inducible factor 1α (HIF-1α) is the core regulatory factor of post-stroke angiogenesis, which can upregulate the expression of key angiogenic factors, such as VEGF and its receptor, thereby promoting post-stroke angiogenesis." (PMID 37622049, 2023). "Research showed that estradiol facilitated neurogenesis in rats after stroke, possibly via increasing HIF-1α and VEGF protein expression." (PMID 35388303, 2022). "Our data suggested that zinc promotes angiogenesis, alleviates brain atrophy, and promotes neurological recovery in experimental stroke through the astrocyte‐mediated HIF‐1α/VEGF signaling pathway." (PMID 35855611, 2022). "We found that zinc promotes angiogenesis via the astrocyte‐mediated HIF‐1α/VEGF signaling pathway in experimental stroke." (PMID 35855611, 2022). "Accumulating evidence elucidated that HIF-1α plays an important role in suppressing oxidative stress and inflammation in stroke." (PMID 35677353, 2022). "HIF-1α controls different pathophysiological processes, including vascular dysfunction, atherosclerosis, myocardial infarction and stroke." (PMID 35741725, 2022). "HIF-1α is an important transcription factor that maintains tissue homeostasis and promotes angiogenesis after stroke." (PMID 35775011, 2022). "In the hypoxic state caused by stroke, the oxygen-dependent HIF prolyl hydroxylase domain (PHD) is inactivated, leading to the stabilization of HIF-1α, followed by its translocation into the nucleus, where it forms a heterodimeric complex with HIF-1β." (PMID 35462700, 2022). "DHA and EPA alleviated post-stroke ischemic damage and behavioral deficits in Wistar rats and downregulated the expression of hypoxia-inducible factor 1 alpha (HIF1α), which is involved in destabilizing BBB integrity." (PMID 35806302, 2022). "The review summarizes the roles of NO•-dependent pathways in the early and late aftermath of stroke and treatments based on the stimulation or inhibition of particular NO• synthases and the stabilization of HIF-1α activity." (PMID 34439764, 2021). "The impact of HIF-1α on neuronal survival upon stroke is controversial, as it mediates both anti- and pro-survival genes." (PMID 34439764, 2021). "In conclusion, HIF-1α plays an important role in the aftermath of stroke and is a promising target for the treatment of ischemic stroke." (PMID 34966392, 2021). "In accordance with our findings, previous studies have shown that serum HIF‐1α concentrations were higher in stroke patients than in the control groups." (PMID 34708885, 2021).
Stroke (continued). "Collectively, these findings indicate that HIF-1α plays a vital role in astrocyte-mediated immune response after stroke." (PMID 34966392, 2021). "Although further verification is needed, HIF-1α will hopefully serve as a predictor of stroke prognosis." (PMID 34966392, 2021). "As a cellular sensor of oxygen level, HIF-1α is now considered as a potential novel therapeutic target for ischemic stroke and will hopefully serve as a predictor of stroke prognosis." (PMID 34966392, 2021). "A recent study showed that the level of HIF-1α in cerebrospinal fluid among stroke patients was lower in patients with cognitive impairment than those without cognitive impairment, an impairment possibly related to BBB damage." (PMID 34493232, 2021). "In the present review, we highlight the neuroprotective and detrimental effects of HIF-1α in in different cell types within the CNS under the context of stroke." (PMID 34966392, 2021). "In ascertaining the contribution of HIF-1α to stroke recovery, we found that DMOG enhanced neuronal cell survival, and improved neuronal soma deficits that had been induced by stroke." (PMID 34205911, 2021). "Our results suggest that HIF-1α improves stroke outcomes by enhancing IL-10 levels, and curtailing iNOS, TNF-α and NF-kB levels." (PMID 34205911, 2021). "HIF-1α activation 12 days post-stroke ameliorated neurological deficit and improved the survival rate." (PMID 34205911, 2021). "Given the role of hypoxia in stroke pathogenesis, the investigation of serum miR‐210 and HIF‐1α as biomarkers were addressed in our present study." (PMID 34708885, 2021). "Hypoxia inducible factor-1 alpha (HIF-1α) is an important regulatory node in reducing oxidative stress and inflammation in stroke." (PMID 34336097, 2021). "Microstructure observations of neuronal soma at 72 h post-stroke showed that HIF-1α activation can improve damaged brain tissue." (PMID 34205911, 2021). "We found that the serum levels of miR‐210 were lower, while serum HIF‐1α levels were higher in stroke patients." (PMID 34708885, 2021). "In the previous study, we demonstrated that HIF-1α played a critical role in the protective effect of RIPC against stroke, which was likely achieved by modulating neuroinflammation in young rats." (PMID 32210788, 2020). "The present results are consistent with previous studies showed that the upregulation of HIF-1α promoted synapse plasticity by mediating synaptic markers, and played a beneficial role in post-stroke exercise inducing angiogenesis and neurogenesis." (PMID 32670026, 2020). "Our previous study showed that HIF-1α was indispensable for RIPC against stroke by modulating inflammation in a young rat model of MCAo." (PMID 32210788, 2020). "Of note, HIF-1α has been reported to have protective effects against a stroke-related injury during hypoxic conditions." (PMID 32796743, 2020). "HIF-1α, the master regulator of the hypoxic response is positioned upstream of all four of these targets and was promoted by rTMS treatment after PT stroke." (PMID 33204331, 2020). "HIF-1α is critically involved in ischemic preconditioning against stroke by modulating inflammatory responses in rats, suggesting that HIF-1α plays a key role in the regulation of HPC protection." (PMID 30203298, 2018). "Hypoxic preconditioned (HP) BMSCs (HP-BMSCs) with increased expression of surviving factors HIF-1α and Bcl-xl (1 × 106 cells/100 μl per mouse) or cell media were administered intranasally at 3, 4, 5, and 6 days after stroke." (PMID 29649974, 2018). "Combined loss of HIF-1α and HIF-2α has been found to be detrimental for functional recovery after ischaemic stroke but surprisingly beneficial in the early stroke phase." (PMID 28968430, 2017). "Thus, our findings suggest that HIF-1α in microglia may be a potential therapeutic target for sparing neuronal loss and reducing neuroinflammation, which can lead to improved functional recovery in stroke patients." (PMID 29340071, 2017).
Stroke (continued). "The HIF-1α signaling is deeply involved in both pathological (hypoxia) and neural repairing (normoxia) pathways after stroke injury." (PMID 29312585, 2017). "Cell type-specific action for HIF-1α has been defined in astrocytes and neurons in a rat neonatal stroke model." (PMID 28855859, 2017). "There has been considerable interest in the importance of HIF regulated pathways in the pathogenesis of stroke yet their role in stroke pathophysiology, particularly HIF-1α, is controversial." (PMID 28968430, 2017). "In this report, strong staining of HIF-1α was observed in 100% (2/2) of GBMs previously with stroke." (PMID 29312585, 2017). "In this short review, we assess the evidence supporting exogenous administration of GSNO after experimental stroke as a means to stimulate neuroregeneration and aid in functional recovery via stabilization of the HIF-1α/VEGF pathway." (PMID 27668143, 2015). "While neuron-specific HIF-1α deletion increased tissue damage after stroke in one study, it reduced ischemic damage in another." (PMID 24409307, 2014). "HIF1A mRNA levels were augmented at 24 h after stroke as were levels of REST, a repressor of neuronal differentiation that was upregulated in the core and PI area at 24 h and 3 d after cerebral infarct." (PMID 23284893, 2012). "This is achieved through the modulation of the HIF-1α/TIM-3 signaling axis in stroke rats." (PMID 41556467, 2026). "Among the validated candidates, miR-199a-5p, miR-3135b, miR-4467, and miR-18a-5p demonstrated diagnostic potential, while miR-4467, together with GNAI2 and HIF1A, showed post-stroke dynamic relevance, reflecting early transcriptomic adaptations following ischemic injury." (PMID 41580787, 2026). "In stroke and chronic inflammation, HIF-1α is stabilized downstream of NF-κB activation." (PMID 38550920, 2024). "Notably, increased activity for multiple of these TFs (e.g. Stat5a, Stat3, Myc, Hif1a, Snai1) was also observed in stroke-specific OPC and Oligodendrocyte subsets." (PMID 39043661, 2024). "While HIF1α function in mammalian stroke has been investigated, studies investigating the role of HIFβ subunits are necessary as they might be valuable targets for future stroke treatments." (PMID 38584778, 2024). "Due to stroke, HIF-1α and EPO starts to accumulate as a response to inadequate oxygen level." (PMID 38302546, 2024). "As a sensitive oxygen homeostasis regulator, HIF‐1α plays an active role in diverse processes concerning the pathophysiology of stroke, with its expression elevated following hypoxia/ischemia, which thus makes it of great importance to reveal the specific role and therapeutic targets for IS." (PMID 39295108, 2024). "HIF1A has been considered an important target for the management of stroke." (PMID 35250546, 2022). "Vascular regulation originates from HIF-1α in endothelial cells, which can promote the formation of new blood vessels in order to protect vascular endothelial cells, nourish neurons, and improve stroke symptoms and prognosis." (PMID 35664672, 2022). "At the same time, the regulation of the brain protein of UCHL1, Hypoxia-inducible factor 1alpha (HIF-1α, 239) may be crucial for how nerve cells repair themselves after a stroke." (PMID 34325669, 2021). "Thus, it seems that the detrimental physiological effects observed by the increased expression of HIF-1α during the early stage of stroke is similar in rodents and humans." (PMID 34447792, 2021). "Several factors have shown important roles in regulating HIF-1α expression after stroke." (PMID 34434231, 2021). "HIF-1α is implicated in hypoxia-mediated inflammasome priming as blockage of HIF-1α reduced expression of NLRP3, caspase 1 and IL-1β and of pyroptotic death in a stroke model." (PMID 34366851, 2021). "The discrepancy in findings between these studies may reflect their use of different timings of interventions and multiple roles of HIF-1α in brain damage process after stroke." (PMID 34336097, 2021).